DISC1 (DISC1 scaffold protein)
Diseases named in the same sentence as DISC1 in open-access papers (continued):
Sharing a sentence is not in itself a finding about the gene and the disease.
schizophrenia (continued). "For example, DISC1 is a gene that is disrupted in schizophrenia patients and is known to be causative factor for schizophrenia and bipolar disorder." (PMID 19091092, 2008). "For example, mice with mutations in Neuregulin-1, Disrupted in schizophrenia 1 (DISC1) and calcineurin, all identified as risk genes for schizophrenia, show impaired working memory." (PMID 18945333, 2008). "YWHAE, a binding partner of DISC1, was also identified as a susceptibility gene for schizophrenia and heterozygous knockout mice of this gene also causes working memory deficits." (PMID 18945333, 2008). "Several "overlap genes" including G72/G30, Neuregulin and DISC1 have now been associated with both schizophrenia and bipolar disorder." (PMID 16232322, 2005). "DISC1-induced and/or partial loss of function in mice resulted in deficits in recognizing memory, social, and anxious behaviors, as well as sensorimotor gating abnormalities, which are typical behavioral symptoms of schizophrenia." (PMID 40537021, 2026). "However, it is known that the loss of disrupted in schizophrenia 1 (DISC1), a scaffold protein involved in synaptic development and neural migration, potentiates Wnt/β-catenin by inhibiting the destruction complex member GSK3β." (PMID 40377402, 2025). "Expanding the analysis to include additional schizophrenia-associated genes such as DISC1, NRG1, COMT, and DTNBP1 could provide a more comprehensive view of the genetic risk factors relevant to our population." (PMID 40977746, 2025). "Introduction of the DISC1-Δ3 gene, a splicing variant of the schizophrenia-associated DISC1 gene, into OPCs induced this pathological phenotype in mice, along with abnormal synaptic formation, altered neuronal activity, and schizophrenic-like behaviors, without affecting myelination." (PMID 40518508, 2025). "Furthermore, investigations have highlighted the involvement of Akt signaling in the operations of genes linked to schizophrenia vulnerability, including DISC-1, NRG-1 and dysbindin-1." (PMID 41283305, 2025). "BDNF, a neurotrophin critical for neuronal survival, migration, differentiation, and synaptic plasticity, is regulated by DISC1, a schizophrenia risk gene modulated by HERV-W env through calcium-dependent Transient receptor potential canonical 3(TRPC3) channel activation." (PMID 41200560, 2025). "Similarly, schizophrenia has been associated with mutations in genes governing synaptic function and neurodevelopment, such as the DISC1 and NRG1 genes." (PMID 40282331, 2025). "Similarly, genetic models of schizophrenia manipulate genes associated with schizophrenia (e.g., DISC-1, dysbindin) individually." (PMID 41254423, 2025). "Similarly, we found increased transcript levels for Disc1, a gene associated with schizophrenia after PB exposure." (PMID 38606173, 2024). "Mutations in DISC-1 are known risk factors for both schizophrenia and BPAD." (PMID 37353479, 2023). "DISC1 has been associated with schizophrenia and is recognized as the risk factor for it." (PMID 36692676, 2023). "Furthermore, carriers of the F607 allele also express lower levels of a DISC1 splice variant expressed in patients with schizophrenia." (PMID 36831241, 2023). "A chromosomal translocation within the human DISC1 is reported to be associated with major mental disorders, including depression, schizophrenia, and bipolar disorder, which may suggest a role of the yak homologue in mental processes." (PMID 37726270, 2023). "RAC1 contributes to the pathogenic mechanism of schizophrenia as the downstream signaling central molecule of several schizophrenia risk genes, including disrupted-in-schizophrenia 1 (DISC1) and brain-derived neurotrophic factor (BDNF), which regulate neuroplasticity and neural connectivity." (PMID 36680208, 2023). "In addition, in brain imaging studies looking at subjects with DISC1 mutant alleles, it was found white matter thickness was significantly reduced, a finding shared with schizophrenia patients." (PMID 35948659, 2023).
schizophrenia (continued). "Recently, DISC1-Δ3, a major DISC1 variant that lacks exon 3, has been identified in schizophrenia patients, although its pathological significance remains unknown." (PMID 36131044, 2022). "Moreover, the schizophrenia risk gene DISC1 affects axonal guidance by activating the Rac-PAK signaling pathway." (PMID 33306168, 2022). "The DISC-1 gene may be one of the genes responsible for the susceptibility to chronic mental disorders, such as schizophrenia, bipolar disorder, and severe, relapsing depression." (PMID 36430976, 2022). "CCDC141 (short for coiled-coil domain containing 141), also named CAMDI after coiled-coil protein associated with myosin II and DISC1 (disrupted in schizophrenia 1), is known to affect neuronal development by impairing radial migration through DISC1 and myosin II-mediated centrosome positioning." (PMID 35350973, 2022). "Furthermore, schizophrenia-associated DISC1 fusion and truncation mutant proteins were shown to inhibit mitochondrial trafficking and fusion thus disrupted normal dendritic development of cultured neurons." (PMID 36344514, 2022). "In addition, previous studies showed that DISC1 undergoes extensive alternative splicing, which is highly regulated by schizophrenia-associated SNPs." (PMID 36131044, 2022). "DISC1 is a schizophrenia risk gene and regulates oligodendroglial development." (PMID 36131044, 2022). "Disrupted-in-Schizophrenia-1 (DISC1), a candidate responsible gene for pathogenesis underlying schizophrenia, plays a role in the post-synaptic density associated with Rac1 The transient and short-term depletion of DISC1 activates Rac1 and induces spine growth in primary cultured neurons." (PMID 36301793, 2022). "The high occurrence of neurological disorders such as schizophrenia, depression or bipolar disorder was linked to the chromosomal translocation of the disrupted in schizophrenia 1 (DISC1) gene, whose protein product inhibited GSK-3β and subsequently activated β-catenin." (PMID 36612190, 2022). "TRAK1 is closely associated with DISC1, itself implicated in schizophrenia and neural development." (PMID 35205252, 2022). "Moreover, in a major mouse model of schizophrenia, in which a human variant of the disrupted in schizophrenia (DISC1) gene is expressed transgenically, the hDISC1 mouse, Snap25 levels are concomitantly decreased." (PMID 35724379, 2022). "In particular, expression of a single gene variant DISC1-Δ3 in the OPCs is sufficient to trigger the onset of schizophrenia-related pathological changes, which may explain the results of previous imaging studies." (PMID 36131044, 2022). "In addition, proteins that were initially identified as risk factors for mental illnesses, such as DISC1 (Disrupted In Schizophrenia) or dysbindin, were later shown to interact with MTs, MAPs, and actin." (PMID 34025352, 2021). "DISC1 and kalirin are also reported to be associated with schizophrenia." (PMID 33315097, 2021). "Some findings may link GSK-3 with the disease: first, GSK-3 is associated with schizophrenia susceptibility genes such as Akt1, DISC1, and TRAX (Translin-associated protein X)." (PMID 35126052, 2021). "For example, proteins encoded by genes mutated in schizophrenia such as dysbindin, DISC1 (disrupted one in schizophrenia) or CRMPs (Collapsin Response Mediator Proteins) were shown to localize to cytoskeleton-rich regions in neurons and to regulate actin and MT dynamics." (PMID 33790791, 2021). "Of the various PDE4 isoforms, those encoded by PDE4B have been most closely associated with schizophrenia and major affective disorders and have been shown to interact directly with DISC1, a protein implicated in neurodevelopment, nuclear functions, and susceptibility to schizophrenia in humans." (PMID 32784895, 2020).
schizophrenia (continued). "We utilize this approach to compare the metabolic composition synaptosomes from a wild-type rat with that from a newly generated genetic rat model (Disc1 svΔ2), which qualitatively recapitulates clinically observed early DISC1 truncations associated with schizophrenia." (PMID 32102223, 2020). "Previous work from our group and others has shown that DISC1 is a positive regulator of mitochondrial transport by interacting with the Miro/TRAK mitochondrial trafficking complex and that schizophrenia-associated DISC1 mutations impair mitochondrial transport, function, and fusion." (PMID 32637409, 2020). "The significance our findings is to link human genetic associations between a common DISC1 gene variant and functional molecular biological changes that could contribute to the pathophysiology of schizophrenia." (PMID 32493513, 2020). "Thus, we sought to discover additional mechanistic links between DISC1 and these other known regulators of psychosis by investigating the functional impact of a schizophrenia-associated DISC1 variant located within the region that binds the D2 receptor." (PMID 32493513, 2020). "A similar reduction of STP has been demonstrated in the CA1 region of mice with Disc1 mutation that modeled a risk allele for schizophrenia, suggesting that reduced STP could be common synapse pathology in schizophrenia." (PMID 30285890, 2018). "In a recent systematic review, it was concluded that DISC1 would have a role in the regulation of dopaminergic function, installing dopaminergic dysregulation as a possible explanation for the higher rate of schizophrenia observed in patients with the DISC1 variant." (PMID 30050571, 2018). "Disc1 is a susceptibility gene for psychiatric disorders including schizophrenia." (PMID 29374282, 2018). "Preliminary in vitro studies demonstrated that two proteins, namely DISC1 and dysbindin-1, which are encoded by two susceptibility genes for schizophrenia, can form insoluble protein aggregates that are reminiscent of those occurring in neurodegenerative disorders." (PMID 30061532, 2018). "Disrupted in schizophrenia 1 (DISC1) is a scaffold protein involved in the regulation of neuronal proliferation, differentiation, migration, and cytoskeletal modulation which has been extensively linked to schizophrenia and other major mental illnesses." (PMID 30050571, 2018). "Disrupted-in-schizophrenia 1 (DISC1) is a gene originally identified as a translocation mutation in an extended Scottish pedigree where carriers suffered from diverse mental disorders comprising schizophrenia and affective disorders." (PMID 29467617, 2018). "In addition, several susceptibility genes for schizophrenia (e.g., DISC1, NRG1/ErbB4, and CRMP2), which are involved in either pre-synaptic DA release or post-synaptic D1R-related cascades, are similarly dysregulated by METH." (PMID 30061532, 2018). "Dysregulated expression of DISC1 may predispose individuals to the development of schizophrenia and other psychiatric conditions." (PMID 30214393, 2018). "Moreover, several genes underlying neuropsychiatric disorders, have been found to be localized to or involved in the formation and maintenance of primary cilia, for example, schizophrenia-associated gene DISC1." (PMID 30713996, 2018). "Most notably, the top-ranked probe associated with PRS in our multi-region model (i.e. across PFC, STR and HC) is located in the gene body of DISC1, a gene previously strongly linked to schizophrenia in a Scottish pedigree with a balanced translocation spanning the locus." (PMID 28011714, 2017). "Given that mutation of DISC1 is implicated in schizophrenia, the pathogenesis of this condition may be related to impaired neuritogenesis." (PMID 28106138, 2017).
schizophrenia (continued). "How and whether the transmissibility of DISC aggregates is linked to the pathogenesis of schizophrenia remains unclear, and further studies are warranted to decipher the mechanism of DISC1 aggregate formation and its implication in the neuropathology of CMI." (PMID 28275106, 2017). "For example, both dysbindin-1 and DISC1 are susceptibility factors for schizophrenia." (PMID 28937620, 2017). "In support of this hypothesis, studies have demonstrated that PDE4B2 and an associated anchoring protein, DISC1 (disrupted in schizophrenia 1), colocalize in neuronal mitochondria." (PMID 28542295, 2017). "For instance, neurons from schizophrenia patients with mutated DISC1, which is thought to have a neurodevelopmental dimension to its pathology, show downregulation of metabolic pathways and LAMA2, a gene in which de novo mutations have been identified in cases of sporadic schizophrenia." (PMID 29051230, 2017). "DISC1 is another schizophrenia susceptibility factor playing roles in neuronal development." (PMID 28937620, 2017). "Unregulated expression of DISC-1 has been associated with schizophrenia and clinical depression." (PMID 26904297, 2016). "Disrupted-in-Schizophrenia 1 (DISC1) is a risk factor for schizophrenia and affective disorders." (PMID 26728762, 2016). "Additionally, the effects of the schizophrenia-associated DISC1-Boymaw fusion protein on mitochondrial dynamics and neuronal development are also poorly understood." (PMID 26553875, 2016). "It implicates that the DISC-1 associated CDC5L complex may explain the epigenetic mechanism in stress-induced prefrontal dysfunction in schizophrenia." (PMID 28117656, 2016). "Mutations in disrupted in schizophrenia 1 (DISC1) may contribute to both schizophrenia and some forms of depression." (PMID 27508065, 2016). "Several studies have implicated 14-3-3 genes with schizophrenia and bipolar disorder, YWHAE and YWHAZ interact with disrupted in schizophrenia 1 (DISC1), and Ywhae+/– and Ywhaz–/– mice have been shown to display neurodevelopmental and schizophrenia-associated phenotypes." (PMID 27142060, 2016). "For the schizophrenia risk locus DISC1, variants were identified from patient pools and tested in Disc1 LOF mouse embryos to determine which could and which could not rescue neuronal progenitor proliferation." (PMID 26092527, 2015). "DISC1 interacts with many other proteins involved in synaptic function, neurodevelopment, the cytoskeleton, and centrosomal pathways, some of which are also associated with schizophrenia and depression (e.g., AKT, DPYSL2, GSK-3β, PDE4, CREB, and β-arrestin)." (PMID 25762938, 2015). "In order to confirm the specificity of sox11 mediated reduction in caspase-6 activity, we co-transfected caspase-6 with two other proteins, FEZ1 which was identified from the yeast-two hybrid screen and DISC1 which is a known susceptibility protein for Schizophrenia." (PMID 26505998, 2015). "These include studies on cortisol and stress neurons derived from hippocampal neurons, DISC1 loss of function in a cortical hNPC model with implication for neuropsychiatric diseases, and knockdown of the schizophrenia and bipolar susceptibility gene, ZNF804a in a cortical hNPC line." (PMID 26296747, 2015). "DISC-1 (Disrupted in Schizophrenia 1) protein, a molecule that determines susceptibility to schizophrenia, is crucial during embryogenesis due to its stimulatory actions on the non-canonical Wnt signaling pathway and its inhibition of glycogen synthase kinase 3-β (GSK-3β)." (PMID 26834550, 2015). "Altered regulation of DISC1 associated with schizophrenia may be interesting due the fact that expression of this gene appears in culture only starting the M-RG stage." (PMID 25799239, 2015). "Moreover, Gomafu regulates genes also associated with schizophrenia such as DISC-1 and ErbB4 and these genes have been shown to be directly involved in neurostructural dynamics." (PMID 26483630, 2015).
schizophrenia (continued). "The effects of MIA on gene expression, DA and 5-HT signaling, neuroanatomy, and the HPA axis may interact with other genetic risk factors such as disruptions in DISC1, which leads to the development of schizophrenia and depression comorbidity." (PMID 25762938, 2015). "We now report on the rs6595788 polymorphism of CTXN3 gene and the rs17817356, rs821597, rs9661837, rs980989 and rs3737597 polymorphisms of DISC1 gene and discuss them as possible risk factors for pathophysiology of schizophrenia in a group of male patients and controls." (PMID 25889058, 2015). "Our hypothesis is that NAP alone and synergistically with other EB3-interacting drugs can effectively improve functional activity in schizophrenia, as tested in the transgenic (Tg) DISC1 mutated mice." (PMID 26553741, 2015). "Furthermore, genetic studies have associated a gene-interplay between SLC12A2 and DISC1 with an altered risk of schizophrenia." (PMID 25889058, 2015). "DISC1 has been linked to the occurrence of schizophrenia and might be related to activity in the kynurenine pathway if this is also related to the disorder." (PMID 26365611, 2015). "Previous studies reported that DISC1 forms aggresomes in multiple cell lines and neurons, raising the possibility that susceptibility protein aggresomes are involved in pathogenesis of schizophrenia." (PMID 27462430, 2015). "Disrupted in schizophrenia 1 (DISC1) is a gene that was implicated in schizophrenia through its discovery as the gene disrupted by a chromosomal translocation that cosegregated with mental illness in a family pedigree prominently affected by schizophrenia, bipolar disorder, and major depression." (PMID 25505409, 2014). "Candidate gene studies have identified a number of genes, such as catechol-O-methyltransferase (COMT), brain-derived neurotrophic factor (BDNF), neuregulin-1 (NRG-1), and disrupted in schizophrenia (DISC-1) that appear to be shared risk factors for schizophrenia, bipolar disorder, and MDD." (PMID 25202283, 2014). "Notably, the schizophrenia and depression susceptibility gene Disrupted in schizophrenia-1 (DISC1) appears to directly bind SR, protecting it from ubiquitin-mediated degradation." (PMID 23630460, 2013). "In vivo, cell proliferation in the adult dentate gyrus could be rescued by administration of a GSK-3β inhibitor, which also suppressed schizophrenia- and depression-like behaviors caused by DISC1 loss of function." (PMID 23805076, 2013). "DISC-1 is a schizophrenia susceptibility gene that regulates multiple steps of neurogenesis." (PMID 23805076, 2013). "While it was initially believed that DISC1 and dysbindin both served as independent susceptibility genes to schizophrenia, a 2011 study investigated whether both DISC1 and dysbindin proteins converged onto a common pathway." (PMID 23618463, 2013). "For example, expression of other actin-related or cytoskeletal proteins has been implicated in schizophrenia and bipolar disorder, and several schizophrenia susceptibility genes interact with actin and the cytoskeleton, including DISC1, calcineurin, Akt1 and dysbindin." (PMID 22675524, 2012). "In addition to DISC1, a number of genes encoding proteins that interact with DISC1 have emerged as promising candidate genes for schizophrenia and other major mental illnesses)." (PMID 22363459, 2012). "Importantly, the protein encoded by the gene “disrupted in schizophrenia-1” (DISC1) directly interacts with GSK3β and suppresses Tyr-216-autophosphorylation and contributes to effective canonical Wnt signaling." (PMID 23083465, 2012).